RN7SKP129 (RN7SK pseudogene 129)
Gene: Miscellaneous RNA gene on chromosome 7 (94,801,514 to 94,801,812, forward strand). Ensembl gene ENSG00000222220.
Homologues: Orthologues: chimpanzee 7SK (100% identical), guinea pig 7SK (66% identical). Paralogues in human: RN7SKP255 (73% identical), 7SK (72% identical), RN7SKP217 (72% identical), RN7SKP9 (72% identical), RN7SKP90 (72% identical), RN7SKP240 (71% identical), RN7SKP243 (71% identical), RN7SKP203 (71% identical), RN7SKP130 (71% identical), RN7SKP211 (71% identical), RN7SKP37 (71% identical), RN7SKP118 (70% identical), and 284 more.